SNORD1B (small nucleolar RNA, C/D box 1B)
Synonyms: R38B; snR38B
Gene: Small nucleolar RNA gene on chromosome 17 (76,561,109 to 76,561,192, forward strand). Ensembl gene ENSG00000199961.
Gene Ontology:
Biological process: RNA processing
Cellular component: nucleolus
Homologues: Orthologues: chimpanzee SNORD1B (99% identical), guinea pig SNORD1B (69% identical), pig SNORD1B (69% identical), rabbit SNORD1B (68% identical). Paralogues in human: SNORD1C (65% identical), SNORD1A (50% identical).